VIP (vasoactive intestinal peptide)
Diseases named in the same sentence as VIP in open-access papers (continued):
Sharing a sentence is not in itself a finding about the gene and the disease.
colon carcinoma (13 papers, 2013 to 2024). "In addition, expression levels of IGKV1-6, IGLV6-57, and CCL28 were higher in colon cancer, while VIP and FABP4 were more biased to be expressed in high-risk group." (PMID 36890467, 2023). "In an azoxymethane-induced mice CRC model, the administration of VIP before and during azoxymethane treatment leads to a significant increase in the incidence of colonic tumors." (PMID 37610689, 2024). "On the other hand, contradictory evidence indicates that VIP attenuates the motility and invasiveness potential of colon cancer cells, and inhibits liver metastasis partly due to the prevention of tumor angiogenesis." (PMID 37610689, 2024). "In conclusion, the present study demonstrated that inhibition of VIP signaling promoted M1 polarization and increased the phagocytic function of TAMs, contributing to a reduction in tumor growth in a colon cancer mouse model." (PMID 36650220, 2023). "Among them, GUCA2A, VIP, and OXTR have been demonstrated to be significantly associated with the prognosis of colon cancer." (PMID 35281839, 2022). "VIP is a polypeptide composed of 28 amino acids whose function is to relax the GI tract and GI sphincter, and it significantly promotes the colon cancer induced by carcinogens in mice." (PMID 28230723, 2017). "Secondly, the target specificity of [F-18]FB-[R8,15,21, L17]-VIP for colon carcinoma, a VIP receptor-positive tumor, was confirmed: high tumor absorption had been shown by 60 min, with the T/M up to 3.03." (PMID 24459669, 2013). "The purpose of this test was to further confirm that the micro-PET imaging outcome was specific radioactivity concentration, proving that the concentration signals were the result of [F-18]FB-[R8,15,21, L17]-VIP and the VIP receptors positively expressed in C26 colon carcinoma tissues." (PMID 24459669, 2013). "To examine the effect of VIP antagonist on tumor growth and TAM function, we implanted CT26 colon cancer cells subcutaneously into immunodeficient SCID mice." (PMID 36650220, 2023). "In conclusion, the inhibition of VIP signaling enhanced M1 macrophage polarization and macrophage phagocytic function, resulting in tumor regression in a CT26 colon cancer model." (PMID 36650220, 2023). "In the current study, we demonstrated that VIP antagonist enhanced M1 markers TNF-α, iNOS, and CXCL10, reduced Mrc-1 mRNA expression, and increased phagocytic ability against CT26 colon cancer cells in mouse macrophage RAW264.7 cells incubated with CT26-CM." (PMID 36650220, 2023). "In the current study, we demonstrated that VIP antagonist enhanced M1 gene expression and phagocytosis of CT26 colon cancer cells in mouse macrophage RAW264.7 cells incubated with conditioned medium derived from CT26 cells." (PMID 36650220, 2023). "In this study, we have further demonstrated the beneficial effect of VIP antagonist on enhancing M1/M2 TAM ratios and macrophage phagocytic function in a colon cancer model." (PMID 36650220, 2023). "Comparisons between the high and low tissue expression of VIP and ZEB1 were performed based on the GSA results, focusing on the EMT and cell cycle pathways in gastric and colon cancer." (PMID 37444395, 2023). "We found that SPP1, VIP, COL11A1, CA2, ADAM12, INHBA could provide great significant prognostic value for colon cancer." (PMID 30746900, 2019). "Neuroendocrine peptides, such as vasoactive intestinal polypeptide (VIP), and calcitonin gene related peptide (CGRP), have been investigated in several studies in colon carcinoma patients and colon cancer experimental models and have been shown to be altered in neurons and nerve fibers." (PMID 27635657, 2016). "Other studies have reported a decrease in VIP expression by nerve fibers, while VIPergic neurons showed no changes in density in human colon cancer." (PMID 27635657, 2016).
Hypertension (13 papers, 2012 to 2025). The presence of chronic increased pressure in the systemic arterial system. "However, some ganglioneuromas may be also functional and secrete peptides, such as VIP and somatostatin, causing diarrhea, hypertension, and sweating." (PMID 35273997, 2022). "Although ganglioneuroma is endocrine-inactive, some ganglioneuromas produce symptoms such as diarrhea, hyperhidrosis, flushing, and hypertension due to the production of catecholamines and vasoactive intestinal peptides (VIP)." (PMID 34098185, 2021). "The VIP levels were shown to be reduced in several models of hypertension and to correlate closely with left ventricular fibrosis." (PMID 25893478, 2015). "Up to 37% of tumors can produce catecholamines or other hormones, with hormonally-induced paraneoplastic syndromes such as diarrhea and hypertension from increased vasoactive intestinal peptide (VIP) or virilization from testosterone secretion." (PMID 22540324, 2012). "Although catecholamine or vasoactive intestinal peptide secretion has been documented in rare cases (potentially causing hypertension/diarrhea), no paraneoplastic syndromes manifested in our cohort." (PMID 41306794, 2025). "What is more, the tumors may occasionally secrete hormones including catecholamine, vasoactive intestinal peptide, and androgen, resulting in hypertension, sweating, diarrhea, or virilization." (PMID 34095202, 2021). "Some patient may have Hypertension and diarrhea if the tumor secretes catecholamine and vasoactive intestinal peptide." (PMID 31220681, 2019).
neuroblastoma (13 papers, 2014 to 2025). Neuroblastoma (NB) is the most common solid, extracranial childhood tumor. "Malignant disease is an uncommon cause of persistent diarrhea and a neuroblastoma presenting with VIP hypersecretion, as in this case report, is a very rare cause of diarrhea (less than 1% of neuroblastomas)." (PMID 40520658, 2025). "Vasoactive intestinal peptide (VIP) significantly reduces MYCN expression in neuroblastoma cells (SH-SY5Y/IMR-32) and exhibits a synergistic inhibitory effect when combined with RA." (PMID 41244073, 2025). "In a French retrospective study, less than 1% of the patients with a diagnosed neuroblastoma had clinical evidence of VIP secretion." (PMID 40520658, 2025). "Patients with VIP-secreting neuroblastoma often exhibit a distinct clinical presentation with chronic diarrhea as one of the first symptoms." (PMID 40520658, 2025). "A study suggests that VIP and PACAP analogs, explicitly developed for therapeutic purposes, can modulate molecular and cellular processes relevant to treating high-risk neuroblastoma." (PMID 38398694, 2024). "In rodents, DXM enhanced the cholinergic nerve terminal development in the brain, the expression of nNOS mRNA in neuroblastoma cells and the growth of VIP mRNA/protein in the Langerhans islets." (PMID 24519145, 2014). "In addition to this, AEA can also increase the levels of VIP in N18 neuroblastoma cells and nerve terminals in rat ileum." (PMID 40003563, 2025). "In vitro, PACAP induced an increased expression of VIP in human neuroblastoma cells, suggesting that PACAP released from nerve terminals could influence the function of VIPergic neurons in target tissues." (PMID 37143998, 2023). "In neuroblastoma cell lines, phorbol ester regulates vasoactive intestinal peptide gene expression." (PMID 28947961, 2017). "Patients with vasoactive intestinal peptide-positive tumors such as GN and neuroblastomas may not have any symptoms or signs of vasoactive intestinal peptide secretion." (PMID 24779851, 2014).
Sepsis (13 papers, 2012 to 2026). Sepsis is defined as life-threatening organ dysfunction caused by a dysregulated host response to infection. "Increased plasma levels of a vasoactive intestinal peptide that causes profound and long-lasting relaxation of the vascular smooth muscle were described in porcine peritonitis-induced sepsis." (PMID 33670874, 2021). "Meanwhile, HMGB1, a late-occurring cytokine, can be downregulated by VIP, as proven in mice, and was critical in endotoxemia and sepsis." (PMID 36499231, 2022). "DPP4i has also been demonstrated to increase the expression of vasoactive intestinal peptide (VIP) in ischemia-reperfusion injury in mouse orthotopic lung transplants and inhibit xanthine oxidase activity to generate ROS in an LPS-sepsis model." (PMID 34681847, 2021). "In a cecal ligation and puncture animal model of sepsis, VIP was shown to retain it protective effects against septic lethality even if administered 24 hours after sepsis induction." (PMID 23305360, 2012). "Moreover, the expression of SP was increased and the level of anti-inflammatory neuropeptide VIP decreased significantly in sepsis group which were reversed by MK-801." (PMID 29440461, 2018). "Additionally, the level of anti-inflammatory neuropeptide VIP was significantly increased in MK-801-treated sepsis animals." (PMID 29440461, 2018). "The complexity of VIP action in sepsis is yet another example of NP duality." (PMID 23305360, 2012). "This review presents a historical assessment of VIP and PACAP in sepsis research, highlighting the evolution of conceptual advances across five decades." (PMID 42117802, 2026). "Across this chronological framework, VIP and PACAP have oscillated between friend, foe, and frenemy, underscoring the importance of context in leveraging their therapeutic potential in sepsis." (PMID 42117802, 2026). "Long lasting VIP secretion by lentiviral-VIP transduced dendritic cells had a therapeutic effect on EAE and cecal ligation and puncture sepsis models." (PMID 26273481, 2015). "VIP and urocortin protect from the lethal effect of E.coli and cecal ligation and puncture (CLP)-induced sepsis and this protection is paralleled by a decrease in the systemic levels of high mobility group box 1 (HMGB1)." (PMID 25101851, 2014). "VIP-secreting VIP-lentivirus-transfected DC are similarly tolerogenic in mouse models of acute and chronic EAE and cecal ligation-and-puncture sepsis." (PMID 24550907, 2014). "VIP, together with neuropeptide Y (NPY), suppresses inflammatory mediator release and increases neuronal tolerance to stress factors during the early phase of sepsis." (PMID 40433666, 2025).
Anxiety (12 papers, 2013 to 2026). Intense feelings of nervousness, tension, or panic often arise in response to interpersonal stresses. "Thus, similar to other mouse strains, in VIP-eGFP mice, aging is associated with decreased locomotion, memory deficits, and anxiety-like behavior." (PMID 33173468, 2020). "In addition to the amygdala, central processing associated with fear and anxiety, has also been shown to involve other VIP-rich regions which are connected to the amygdala by interneurons—such as the hippocampus and prefrontal cortices thus forming an anatomically connected “microcircuit”31." (PMID 33446759, 2021). "In agreement with previous work, we found no significant impairments in percentage of time spent in the open arms of the elevated plus maze task, a measure of anxiety, for the Dlx5/6, VIP, PV, or SST mutants compared to controls." (PMID 32343226, 2020). "That study found VIP interneurons normally facilitate the transmission of anxiety-related information from the vHPC to mPFC by disinhibiting prefrontal responses to vHPC input." (PMID 33155545, 2020). "Anxiety-depressive states could result in altered SS and VIP secretion, which in turn affects gastrointestinal motility and function." (PMID 38601933, 2024). "As a result, when VIP interneurons are inhibited, information about anxiety is not transmitted properly, causing mice to spend more time exploring the open arms." (PMID 33155545, 2020). "Anxiety-depressive states may lead to changes in the secretion of SS and VIP, and subsequently to changes in gastrointestinal motility and function." (PMID 24137253, 2013). "In addition, the expression levels of SS and VIP in the IBS groups with normal emotional state ratings were notably different from those in the IBS groups in anxiety-depressive states (P<0.05)." (PMID 24137253, 2013). "Ablation of mPFC VIP neurons did not change the locomotor activity or anxiety-like behaviors of these mice during the OFT, which indicated that the change in immobility was not likely due to motor defects." (PMID 41409708, 2025). "The data presented here indicate that ablation of VIP interneurons in the IL is sufficient to drive impulsivity without increasing novelty-seeking or anxiety-like behaviors." (PMID 37267385, 2023). "VIP ablation in the mPFC led to a specific increase in impulsive responding during long-delay trials, with no non-specific effects on anxiety-like behaviors or food-related motivation, revealing a novel role of VIP neurons in the control of impulsive behavior." (PMID 37267385, 2023). "These behavioral changes occur without increasing anxiety-like behavior or palatable food intake, implicating VIP IL interneurons in the specific control of impulsive responding." (PMID 37267385, 2023). "Furthermore, the expression levels of SS and VIP in the blood, colonic mucosa and sigmoid colonic mucosa were higher in the patients with IBS in anxiety and depressive states than in those with normal emotional state ratings." (PMID 24137253, 2013). "Furthermore, chemogenetic inhibition of mPFC VIP neurons did not affect locomotion or anxiety-related behaviors during the OFT." (PMID 41409708, 2025). "Similarly, chemogenetic inhibition of mPFC VIP neurons did not affect locomotion or anxiety-related behaviors during the OFT." (PMID 41409708, 2025).
COVID-19 (12 papers, 2020 to 2025). A disease caused by infection with severe acute respiratory syndrome coronavirus 2. "In patients with severe COVID-19, elevated plasma levels of the immunomodulatory neuropeptide VIP were associated with a reduction in inflammatory mediators and survival in these patients." (PMID 36626425, 2022). "Aviptadil, a synthetic form of human vasoactive intestinal peptide, might be beneficial for COVID-19 patients at high risk of developing ARDS because of its ability to influence the regulation of exaggerated pro-inflammatory proteins and orchestrate the lung homeostasis." (PMID 36127739, 2022). "Patients with severe coronavirus disease 2019 (COVID-19) had significantly higher plasma levels of VIP as compared to patients with mild COVID-19 symptoms and noninfected healthy individuals, and these high levels were associated with better survival." (PMID 37146001, 2023). "Other immunotherapies for diseases such as COVID-19 target the vasoactive intestinal peptide or VIP, which modulates the balance between pro- and anti-inflammatory responses with promising results." (PMID 37065208, 2023). "Recent data demonstrated that plasma levels of VIP are higher in patients with severe COVID-19, compared to healthy individuals and those with mild COVID-19, and that VIP can block SARS-CoV-2 virus replication in vitro." (PMID 36127739, 2022). "A recently published study corroborates this finding in COVID-19 patients, where the plasma VIP levels were raised in patients with severe COVID-19, correlating with reduced inflammatory mediators and with survival in these patients." (PMID 35955723, 2022). "We now show that the same ViP signatures can objectively demonstrate the shared immunophenotypes between all three syndromes (COVID-19, KD and MIS-C), which features an upregulation of the IL15/IL15RA pathway." (PMID 35577777, 2022). "There are ongoing trials to explore the role of specific therapies for PH, such as ambrisentan, sildenafil, iloprost, iNO, recombinant ACE2, vasoactive intestinal peptide (VIP) analog, and tocilizumab in COVID-19." (PMID 33352654, 2020). "Our present data show how VIP can hamper viral entry mechanisms in the example of COVID-19." (PMID 40141308, 2025). "Interestingly, in agreement with these studies, our results show the upregulation of enteric nNOS and VIP neurotransmitters, indicating intensified gut motility patterns in COVID-19 patients." (PMID 36830577, 2023). "The resultant 166-gene ViP signature, developed from just two training datasets of pandemics of the past, was found to be conserved in all viral pandemics and outbreaks, including prospective studies on all COVID-19 datasets." (PMID 35577777, 2022). "Finally, in the case of the hiPSC-derived AT1/2 organoids, which recapitulated the COVID-19-lung derived immune signatures, the 166-gene ViP signature was induced significantly (top), but the 20-gene severity signature was not (bottom)." (PMID 34463615, 2021). "Thus, the ViP signatures begin to paint a picture of ‘paradoxical immunosuppression’ at the heart of fatal COVID-19, in which, the observed NK cell exhaustion/depletion in severe COVID-19 could be a consequence of an overzealous IL15 storm, leading to their senescense and apoptosis." (PMID 34127431, 2021). "This SNP has not been studied in COVID-19, but VIP levels were increased in patients with severe disease and correlated with lower levels of inflammatory biomarkers and survival of those patients." (PMID 37809329, 2023).
endotoxemia (12 papers, 2012 to 2026). "Whereas, some reports reveal that VIP-deficient mice are resistant to the development of induced-encephalomyelitis or induced-endotoxemia indicating that in these conditions VIP plays unexpected permissive and/or pro-inflammatory actions." (PMID 23162538, 2012). "However, there are discrepancies about the resistance or susceptibility of VIP-KO mice to endotoxemia." (PMID 31861827, 2019). "On the other hand, some studies have reported that a deficiency of VIP may support resistance to lipopolysaccharide-induced endotoxemia." (PMID 29255488, 2017). "Starting in the 1980s, early studies revealed that VIP levels rise during endotoxemia and correlated with hypotension and mortality, suggesting a deleterious role." (PMID 42117802, 2026). "Here, we used the LPS model of endotoxemia and we found that VIP KO mice exhibited reduced mortality, less tissue injury, and impaired proinflammatory responses." (PMID 22615845, 2012). "In our model of endotoxemia we found a transient increase in VIP plasma concentrations." (PMID 23651810, 2013). "As a model to test this hypothesis, we investigated the response of VIP KO mice to LPS-induced endotoxemia." (PMID 22615845, 2012). "These and other previous studies showed that VIP downregulates TNFα expression in LPS-treated RAW264.7 cells and activated microglia, and in vivo in models of nerve injury and endotoxemia." (PMID 34025407, 2021). "Endogenous neuropeptides, specifically vasoactive intestinal peptide (VIP) and urocortin, acted as inhibitors of HMGB1 cytokine activity that increased the survival of animals with established endotoxemia." (PMID 28127491, 2017). "At this point, we can only hypothesize why the lack of VIP results in decreased inflammation in the models of EAE and LPS-induced endotoxemia." (PMID 22615845, 2012).